COL18A1 (collagen type XVIII alpha 1 chain)
Diseases named in the same sentence as COL18A1 in open-access papers (continued):
Sharing a sentence is not in itself a finding about the gene and the disease.
tumor (48 papers, 2007 to 2025). "COL18A1, or endostatin, is a basement membrane protein, which has been implicated in tumour growth and angiogenesis." (PMID 31454915, 2019). "This region of COL18A1 also encodes for a cleavable protein called endostatin that has been shown to be anti-angiogenic and inhibit tumor formation." (PMID 25392994, 2014). "In summary, this study identified collagens type IV, VI, VII, X, XIV, XV, XVI and the short variant of COL18A1, NC1-301, as tumor-associated collagens in HCC." (PMID 21731504, 2011). "Interestingly, the variant of rhabdomyosarcoma cell cultures that produce COL18A1 is the ‘alveolar’ subtype, thus called because rich collagen stroma encasing the tumor cells is reminiscent of lung histology." (PMID 33708626, 2021). "RFC1 transport function is enhanced by another protein, Collagen alpha-1 (XVIII) chain, encoded by COL18A1 (locus 21q22.3), and has been described as crucial for malignant processes due to endostatin production, which is a powerful angiogenesis and tumor growth inhibitor." (PMID 27547186, 2016). "Among these genes, several immune system genes, such as COL18A1, S100A2, ITGA4, HLA‐C, and ADCYAP1, have previously been linked to tumor progression in PCa." (PMID 39162297, 2024). "Immunostaining of the WT-PyMT tumor allografts showed prominent ColXVIII signals at the borders of the tumor nests in the WT hosts but somewhat weaker signals at these sites in the Col18a1–/– hosts." (PMID 37498672, 2023). "Expression of COL18A1 and PLOD2 is associated with increased tumor infiltration, metastasis, and worse overall survival and thus offer potential therapeutic targets." (PMID 33708626, 2021). "Examination of cluster-specific marker genes showed that tumor ECs expressed a unique set of genes such as Col18a1 and Aplnr, but also shared a number of expressed genes with venous ECs, especially with PV, such as Cd63, Ehd4, and Cd200." (PMID 32440964, 2020). "CSCs are not only responsible for sustaining primary tumors, but are also connected with the metastatic dissemination of neoplastic clones to distant organs, and we show here that both the primary tumor burden and lung colonization were reduced in mice with Col18a1 depletion." (PMID 37498672, 2023). "Reciprocal orthotopic allograft transplantations between the WT and Col18a1–/– genotypes were performed to determine whether the tumorigenic functions of ColXVIII are tumor cell autonomous or microenvironmental." (PMID 37498672, 2023). "Furthermore, modification or cleavage of COL18A1 (e.g. endostatin) perhaps alters tumor biology e.g., dysregulating tumoral angiogenesis or increasing metastatic potential." (PMID 33708626, 2021). "COL18A1 encodes a potent antiangiogenic protein that can inhibit angiogenesis and HCC tumor growth." (PMID 34252885, 2021). "Similar to luminal cluster 2 in primary tumour, cluster 3 in lung mets, was enriched in a proliferation gene signature (Ran, Cks1b, and Cks2), whereas cluster 2 (homologous to cluster 3 in primary tumour), expressed a mesenchymal-like gene set (Col18a1, Vcam1, Col1a1, Vim, Sparc)." (PMID 38238426, 2024). "We found that the expression levels of seven integrin ligands (COL4A6, COL13A1, FGB, COL19A1, COL18A1, COL14A1, and COL11A2) were negatively correlated with the Gleason score, suggesting that the suppression of integrins and/or their ligands is associated with more advanced tumor grade." (PMID 19653896, 2009). "The expression of the epithelial transcript marker EPCAM coincided with the expression of COL18A1, TNC and COL12A1 gene transcripts in the tumor clusters." (PMID 39239354, 2024). "LUM, COL18A1, BGN, PRELP, and ASPN showed increased expression in tumor tissue compared to the paired NAT tissue, inconsistent with the declined trend in other histologic subtypes." (PMID 39305996, 2024).
tumor (continued). "In the Col18a1–/– hosts, the tumors were on average half the size of those in the WT hosts by the same week, and although the difference was not statistically significant, this observation suggested that host-derived ColXVIII could also have contributed to the regulation of tumor growth." (PMID 37498672, 2023). "Instead, genes that codify for tumor suppressors, such as those of collagen type XVIII alpha 1 chain (COL18A1), collagen type 1 alpha 2 chain (COL1A2), as well as that for natriuretic peptide receptor 3 have been downregulated." (PMID 36548750, 2022). "CNA gains of suppressor genes are enlisted by gains of HADAC3 in 18 HRO-, COL18A1 in 16 HRO-, TGFBI in 16 HRO- and CDH4 in 15 HRO tumours." (PMID 28486536, 2017). "Several other collagen α chains, including COL18A1, were upregulated in dormant cells, but their inhibition did not disrupt tumor dormancy in vivo, further supporting the notion that high ColXVIII expression is implicated in tumor promotion." (PMID 37498672, 2023). "Studies using Col18a1 mouse models crossed with the mouse mammary tumor virus–polyoma virus middle T antigen (MMTV-PyMT) mammary carcinogenesis model showed that ColXVIII promoted BC growth and metastasis in a tumor cell–autonomous manner." (PMID 37498672, 2023). "Another matrix CAF subcluster, C11, was linked to angiogenesis and highly expressed NOTCH3 (an important receptor in vascularization and angiogenesis), COL18A1 (involved in angiogenesis regulation), COL4A1, and COL4A2, which might promote the proliferation and metastasis of tumor." (PMID 38010945, 2024). "Additionally, COL18A1 and PGF were screened as tumor cell hub ligands in branches I and II." (PMID 33971970, 2021). "The data obtained from these tumours are also consistent with an upregulation of anti-angiogenic ING4 mRNA levels in the human xenograft tumours in vivo, with no significant changes are detected for ANG, VEGFA, HIF1α, THBS2 and COL18A1." (PMID 35513564, 2022).
cancer (26 papers, 2007 to 2026). A tumor composed of atypical neoplastic, often pleomorphic cells that invade other tissues. "Among these, eight plasma proteins were associated with mortality, with COL18A1 showing the highest HR in all cancer patients (HR[95%CI] = 1.72[1.92–2.50])." (PMID 38734658, 2024). "Five mutated gene variants that were transferred to the BRCA1-KO fibroblasts (BTN3A2, DDX51, LARP6, AP1G1 and COL18A1) were found to be also present as RNA variants following RNA sequencing of BRCA1-KO fibroblasts after exposure to cancer EVs." (PMID 31200749, 2019). "Genes labeled by IPA as being cancer related (COL18A1, STAT5B, CTDSPL) were also involved with infection as were genes involved in apoptosis and growth (CTDSPL, POLR2F, ZBTB16)." (PMID 18047719, 2007). "The highest expression of genes encoding Col1a1-2, Col3a1, Col4a1, Col4a2, Col5a1, Col5a2, Col6a1, Col8a1, Col9a3, Col10a1, Col12a1, Col14a1, Col15a1, Col16a1, Col18a1, and Col28a1 were detected in untreated tumors, whose landscapes were dominated by Krt8+ cancer cells." (PMID 39372930, 2024). "As an example, some collagen isoforms inhibiting cancer cell proliferation, i.e., Collagen type XVIII alpha 1 chain (COL18A1) and collagen type I alpha 2 chain (COL1A2), were downregulated." (PMID 32610656, 2020). "Two more (COL18A1 and COL1A2) were collagen genes possessing inhibitory effects on cancer cell proliferation." (PMID 32610656, 2020). "Thus, COL18A1, when normally expressed, may aid in the prevention of cancer." (PMID 29983747, 2018). "In Elyada’s scRNA-seq analysis, ductal cancer cells in human PDAC were clustered in two major subtypes: the classic (by TFF1, TFF2, LYZ, VSIG2, and CEACAM6 marker genes) and secretory (by SPP1, CLU, CTGF, and COL18A1 marker genes) subtypes." (PMID 34035226, 2021). "Besides, COL18A1 is a regulator of the oxidative stress response and has been suggested that the potential links between ECM and oxidative stress response in cancer." (PMID 31217907, 2019). "These early differences between L–E and H/W may indicate that Col18a1 is involved in the early stages of TCDD hepatotoxicity, while the late difference may indicate it also is involved in TCDD-induced cancer or other delayed toxicities." (PMID 27136898, 2017). "The observed down-regulation of several extracellular matrix and basement membrane proteins, such as COL18A1 and NID2, could have great consequences on the integrity of the tissue and lead to altered differentiation (KRT4) and cancer-like alterations that may explain the characteristic phenotype." (PMID 25093596, 2014).
infection (11 papers, 2007 to 2025). The state of being infected such as from the introduction of a foreign agent such as serum, vaccine, antigenic substance or organism. "Women with parasitological clearance post-praziquantel, compared to those without infection at baseline, had lower expression of the gene Collagen type I alpha 1 (COL18A1)." (PMID 41270010, 2025).
cardiac disease (1 paper, 2016). "COL18A1 (OMIM: 120328) mutations affect non-cardiac tissues and have not been implicated in cardiac disease." (PMID 26815362, 2016).
cardiovascular diseases (1 paper, 2025). "Some of these genes are strongly associated with cardiovascular diseases, such as the MUC family, COL18A1, and TNXB." (PMID 40963926, 2025).
kidney disease (1 paper, 2025). "Among the remaining proteins, some are associated with chronic inflammation in kidney disease (Chil3 and Mmp8), others are components of the glomerular basement membrane (Col18a1), and others have an uncertain function in kidney disease." (PMID 39911133, 2025).
COL18A1 also shares sentences with these, for which no sentence is quoted: angioedema (17 papers); hereditary angioedema (11); melanoma (5); occipital encephalocele (5); Down syndrome (3); lung carcinoma (3); vitreoretinal degeneration (3); autoimmune condition (2); autoimmune disease (2); genetic diseases (2); glomerulonephritis (2); Intellectual disability (2); liver disease (2); Marfan syndrome (2); acute myeloid leukemia (1); acute respiratory distress syndrome (1); adenoma (1); adrenal cancer (1); allergies (1); Alport syndrome (1); Alzheimer disease (1); anemia (1); asthma (1); Batten disease (1); C1 inhibitor deficiency (1); Canavan disease (1); CHARGE syndrome (1); chondrodysplasia (1); chronic obstructive pulmonary disease (1); colon carcinoma (1).
A further 54 diseases each share a sentence with COL18A1 in 1 paper.